ATP6V0A1 (ATPase H+ transporting V0 subunit a1)
Description:
Subunit of the V0 complex of vacuolar(H+)-ATPase (V-ATPase), a multisubunit enzyme composed of a peripheral complex (V1) that hydrolyzes ATP and a membrane integral complex (V0) that transports protons across cellular membranes. V-ATPase is responsible for the acidification of various organelles, such as lysosomes, endosomes, the trans-Golgi network, and secretory granules, including synaptic vesicles. In certain cell types, can be exported to the plasma membrane, where it is involved in the acidification of the extracellular environment (By similarity). The V-ATPase complex also acts as an activator for mTORC1 on lysosomal membrane by promoting the guanine nucleotide exchange factor (GEF) of the Ragulator complex, thereby enabling mTORC1 recruitment. Required for assembly and activity of the vacuolar ATPase (By similarity). Through its action on compartment acidification, plays an essential role in neuronal development in terms of integrity and connectivity of neurons.
Synonyms: ATP6N1; ATP6N1A; VPP1; a1; Vph1; Stv1; DEE104; NEDEBA
Tractability: Small molecule: a structure with a bound ligand is known. Antibody: its Gene Ontology location is reachable by antibodies, with high confidence; UniProt predicts a signal peptide or a membrane-spanning region. PROTAC: ubiquitination databases record sites on it; its protein half-life has been measured.
Gene: Protein-coding gene on chromosome 17 (42,458,844 to 42,522,582, forward strand). Ensembl gene ENSG00000033627.
Subcellular location: Cytoplasmic vesicle, clathrin-coated vesicle membrane; Cytoplasmic vesicle, secretory vesicle, synaptic vesicle membrane; Melanosome
Subcellular location (Human Protein Atlas): Golgi apparatus; Vesicles; Cytosol; Nuclear speckles
Pathways (Reactome):
Immune System: Neutrophil degranulation; ROS and RNS production in phagocytes
Transport of small molecules: Ion channel transport; Transferrin endocytosis and recycling
Developmental Biology: Regulation of MITF-M-dependent genes involved in lysosome biogenesis and autophagy
Signal Transduction: Insulin receptor recycling
Gene Ontology:
Molecular function: ATPase binding; protein binding; proton-transporting ATPase activity, rotational mechanism
Biological process: regulation of macroautophagy; endosomal lumen acidification; lysosomal lumen acidification; proton transmembrane transport; vacuolar acidification; synaptic vesicle lumen acidification
Cellular component: extracellular exosome; melanosome; membrane; plasma membrane; endosome membrane; ficolin-1-rich granule membrane; lysosomal membrane; phagocytic vesicle membrane; proton-transporting V-type ATPase complex; secretory granule membrane; vacuolar proton-transporting V-type ATPase complex; vacuolar proton-transporting V-type ATPase, V0 domain; clathrin-coated vesicle membrane; cytoplasm; perinuclear region of cytoplasm; proton-transporting V-type ATPase, V0 domain; synaptic vesicle membrane
Genetic constraint (gnomAD): Loss-of-function variants: 31 observed, 87.49 expected, observed/expected ratio (o/e) 0.35, 90% interval 0.26 to 0.48. The upper end of that interval is the gene's LOEUF score, 0.48, which puts it in group 2 of 6, group 1 being the genes least tolerant of losing a copy. Missense variants: 620 observed, 1,005.7 expected, observed/expected ratio (o/e) 0.62, 90% interval 0.58 to 0.66. Synonymous variants: 337 observed, 361.1 expected, observed/expected ratio (o/e) 0.93, 90% interval 0.85 to 1.02.
Homologues: Orthologues: chimpanzee ATP6V0A1 (99% identical), macaque ATP6V0A1 (99% identical), dog ATP6V0A1 (97% identical), rabbit ATP6V0A1 (97% identical), rat Atp6v0a1 (96% identical), mouse Atp6v0a1 (96% identical), guinea pig ATP6V0A1 (95% identical), pig ATP6V0A1 (94% identical), tropical clawed frog atp6v0a1 (89% identical), zebrafish atp6v0a1b (84% identical), zebrafish atp6v0a1a (82% identical), Drosophila melanogaster Vha100-1 (62% identical), and 7 more. Paralogues in human: ATP6V0A4 (62% identical), ATP6V0A2 (55% identical), TCIRG1 (46% identical).